AHR (aryl hydrocarbon receptor)
Diseases named in the same sentence as AHR in open-access papers (continued):
Sharing a sentence is not in itself a finding about the gene and the disease.
infection (continued). "However, given that LPS treatment markedly increased AHR and AHRNT mRNA expression in murine B cells and splenocytes, it is possible that low level LPS translocation from a leaky intestinal epithelial barrier early in infection might provide the stimulus for AHRT gene activation." (PMID 22511950, 2012). "Moreover, this provides a potential explanation for how AHR activation during development affects the ability of DCs to activate naïve CD8+, but not CD4+ T cells, following infection." (PMID 30412605, 2018). "Moreover, and in contrast to that observed when AhR was activated by exogenous ligands, the frequency of CD8+ total and T. cruzi-specific T cells with EM phenotype was higher in AhRd than WT mice at 17 days pi and during the chronic phase of the infection (day 170 pi) (not shown)." (PMID 30984194, 2019).
metabolic disorders (61 papers, 2012 to 2026). "This study encompassed the effects of BaP on lipogenesis, decomposition, inflammation, and a series of metabolic disorders caused by AhR in in-vivo and external settings." (PMID 35057794, 2022). "Metabolic diseases caused by BaP are related to the unhealthy expansion of WAT caused by AhR, including increaseing inflammatory factors, inhibiting fat formation and FFA transport." (PMID 35057794, 2022). "This is also true of several molecules, such as FXR and AhR, whose activation has been associated with both beneficial and harmful effects on metabolic disease." (PMID 35873002, 2022). "A recent study reported that the symptoms of a metabolic disorder were associated with a reduced microbial capacity to transform tryptophan into AhR agonists." (PMID 34631603, 2021). "Apart from metabolic diseases, AhR activation leads to alternative susceptibility to infection and inflammation." (PMID 34297785, 2021). "Disturbance in Trp metabolism and/or AhR activation is strongly associated with multiple gastrointestinal, neurological and metabolic disorders, suggesting Trp metabolites/AhR signaling modulation as an interesting therapeutic perspective." (PMID 32957545, 2020). "Nevertheless, the molecular mechanisms underlying the AhR activation on metabolic diseases are very complex, and the outcomes vary during the development of diseases." (PMID 27292372, 2016). "More recently, many lower-affinity agonists of AhR have been identified from commercial and consumer products, fruits, and vegetables to exhibit a wide variety of physiological functions in different metabolic diseases." (PMID 40197001, 2025). "We further examined the role of hepatic AhR was investigated in mediating these effects to better understand how AhR activation contributes to the pathogenesis of metabolic disorders." (PMID 40943373, 2025). "The critical role of AhR in PPARγ stability represents the potential of AhR as a therapeutic target for metabolic disease treatment." (PMID 38931457, 2024). "Microbial tryptophan (Trp) metabolites acting as aryl hydrocarbon receptor (AhR) ligands are shown to effectively improve metabolic diseases via regulating microbial community." (PMID 39041942, 2024). "Specifically, we highlighted the possible use of AhR as a therapeutic target for metabolic disease treatment." (PMID 38931457, 2024). "This AhR–PPAR interaction has recently gained interest as a potential therapeutic target for metabolic diseases." (PMID 39114118, 2024). "Overall, (‐) Leu‐B. coccoides‐I3AA axis activated liver AhR and contributed to the improvement of metabolic disorders." (PMID 38429906, 2024). "A recent study indicated that individuals exhibiting metabolic disorder symptoms had a diminished microbial capacity to convert tryptophan into compounds that activate the aryl hydrocarbon receptor (AhR)." (PMID 39200318, 2024). "Aryl hydrocarbon receptor (AhR) is a transcription factor that regulates ligand activation of foreign body metabolic disease." (PMID 35979373, 2022). "AhR regulates PPARγ stability and AhR–PPARγ interaction is a potential therapeutic target for metabolic diseases." (PMID 34432833, 2021). "What is interesting is that some human studies showed an association between exposure to AhR agonists (especially TCDD) and an increased risk of developing T2D and other metabolic disorders like hyperlipidemia or obesity." (PMID 34199713, 2021). "In this review, we re-trace the steps through which the early toxicological studies of TCDD led to the conceptual framework for the AHR as a potential therapeutic target in metabolic disease." (PMID 33374508, 2020). "The role of proteolytic fermentation in health goes beyond metabolic disease, as metabolites of aromatic amino acid metabolism are capable of binding the aryl hydrocarbon receptor (AhR)." (PMID 30642098, 2019).
metabolic disorders (continued). "Other environmental toxins, such as TCDD, particulate matters, and benzo[a]pyrene, have been reported to promote metabolic diseases through AhR activation." (PMID 29285309, 2017). "Future research should systematically compare the effects of different agonists, antagonists, and selective AhR modulators (sAhRMs), aiming to screen or design targeted AhR therapies for metabolic diseases that can harness its benefits while mitigating its detrimental effects." (PMID 41585883, 2025). "The ability of gut microbes to metabolize tryptophan is reduced, which lowering the activation of AhR to promote metabolic disease, suggesting that AhR may regulate lipid metabolism through the gut microbiota." (PMID 39944639, 2025). "The aryl hydrocarbon receptor (AhR), initially known as a transcription factor linked to the toxicity of various xenobiotic compounds such as TCDD, also may be responsible for metabolic disorders linked to MDCs." (PMID 39218795, 2024). "In addition to cancersand metabolic diseases, circadian disruption has also been known tobe influenced by these pollutants via AhR activation." (PMID 39072055, 2024). "Various studies, including human cohort studies, support that inhibition of the AhR pathway or aberrant AhR activation may be a good therapeutic strategy for metabolic diseases." (PMID 36499198, 2022). "Collectively, these studies demonstrate that an intrinsic increase in the expression of AhR and its activity through endogenous and exogenous ligand factors has the potential to exert multifaceted influences on the pathophysiology of metabolic disorders, including DM." (PMID 36418969, 2022). "In addition, AhR agonists or Lactobacillus regulation can be an available treatment to reverse metabolic disorders." (PMID 34631603, 2021). "BPA can promote metabolic disorders through its endocrine-disrupting effect on multiple nuclear receptors, including the estrogen, glucocorticoid (GR), and aryl hydrocarbon receptor (AhR)." (PMID 35295127, 2021). "Thus, the effects of the different samples on the expression of AhR, as a key player in diet-induced adiposity and metabolic disorders influencing energy expenditure, were studied." (PMID 30134638, 2018). "Further, dietary TCDF inhibited the farnesoid X receptor (FXR) signaling pathway, triggered significant inflammation and host metabolic disorders as a result of activation of bacterial fermentation, and altered hepatic lipogenesis, gluconeogenesis, and glycogenolysis in an AHR-dependent manner." (PMID 25768209, 2015). "Based on recent studies, the fundaments of current risk assessment of POPs, like “concept of additive effects” or “dioxins and dl-PCBs induced similar biological effects through AhR”, appear unlikely to predict the risk of metabolic diseases." (PMID 22520265, 2012). "Therefore, the use of inhibitors or knockout of AhR could effectively rescue BPA-induced metabolic disorders in PCOS mice." (PMID 38200540, 2024). "In addition, AhR agonists or Lactobacillus regulation may be a treatment available to reverse metabolic disorders." (PMID 39200318, 2024). "The aromatic hydrocarbon receptor (AhR) is distributed in almost all tissues in various mammals and is expressed abundantly in the placenta, liver, and lungs, where it plays multiple roles in regulating the immune response, carcinogenesis, metabolic diseases, and neurophysiology." (PMID 34966278, 2021). "Therefore, intrinsic increase in AHR expression, together with environmental factors influencing AHR signaling (such as endogenous or exogenous ligands), may exert multifaceted influence in the pathophysiology of the metabolic disorders." (PMID 32849564, 2020). "AhR can also regulate fibroblast growth factor 21 (FGF21), which protects properties against metabolic disease by promoting energy expenditure and improving both lipid and glucose metabolism." (PMID 35887027, 2022).
metabolic disorders (continued). "For some complex metabolic diseases, such as CVD, NAFLD, and T2DM, IPA participates in disease treatment by stimulating corresponding receptors such as PXR or AHR through the specific gut–organ axis." (PMID 36615808, 2022). "AHR genetic (AhR−/− and AhR−/+) mice have been employed to comparatively investigate the possible roles of AHR in various physiological and pathological processes, including diet-induced metabolic diseases." (PMID 33622853, 2021). "Modulating AHR signaling through changes in the gut microbiome may be a novel treatment for metabolic diseases." (PMID 34065241, 2021). "Therefore, the therapeutic strategy of targeting pathological AhR activation—without abolishing physiological signaling—may offer a balanced approach to managing pollutant-driven metabolic diseases." (PMID 40943373, 2025).
cardiovascular disease (38 papers, 2009 to 2025). "Activation of AhR also increases the risk of cardiovascular diseases because of increased expression of cyclooxygenase-2 and, in turn, the accelerated synthesis of prostaglandin and thrombin." (PMID 37233670, 2023). "Taken together, these findings indicate that the activation of AhR is a key mechanism associated with deleterious cardiovascular disease in CKD." (PMID 31488157, 2019). "The AhR is closely associated with cardiovascular disease in terms of cardiac function, vascular development and blood pressure regulation." (PMID 31638212, 2019). "The findings reported here underscore the conclusion that AHR signaling in the developing heart is one potential target of environmental factors associated with cardiovascular disease." (PMID 26555816, 2015). "Mitochondrial dysfunction has been associated with AHR signaling disruption in vitro and in vivo, and extensively investigated as a key player in cardiovascular disease." (PMID 26555816, 2015). "AhR activation by 2,3,7,8-tetrachlorodibenzo-p-dioxin and some polychlorinated biphenyls is associated with an increase in cardiovascular disease in humans and in mice." (PMID 24599232, 2014). "Activation of AHR signaling can trigger oxidative stress and inflammation, by which tryptophan-derived uremic toxins are closely associated with the development of cardiovascular disease." (PMID 35326133, 2022). "Importantly, several gut microbiota-derived uremic toxins are associated with cardiovascular disease (CVD) in CKD via the activation of the aryl hydrocarbon receptor (AHR)." (PMID 34683012, 2021). "Recently, developmental interference with endogenous Aryl Hydrocarbon Receptor (AHR) functions has been shown to adversely affect the cardiovascular system in various experimental models, and have implicated the AHR in the etiology of cardiovascular disease." (PMID 29367575, 2016). "For initial studies we have chosen the AHR gene, because it encodes a transcription factor, allowing direct study of its downstream signaling pathway, and because of the well-characterized link between this factor and environmental exposures that are relevant for cardiovascular disease." (PMID 28481916, 2017). "In summary, this leads to the conclusion that AhR seems to have a profound negative impact on healthy aging as well as on the cardiovascular system and that AhR expression might be a useful, additional marker for vessel functionality in the prediction of age-associated cardiovascular diseases." (PMID 26790370, 2016). "These compounds can activate the aryl hydrocarbon receptor (AhR) in the vasculature, promoting oxidative stress and driving pathological processes such as inflammation and cardiovascular disease." (PMID 40864097, 2025). "AhR-mediated signaling plays an important role in CKD complications such as cardiovascular disease, bone disorders, and thrombosis, making AhR antagonists a promising therapeutic strategy." (PMID 39684480, 2024). "The potential for AHR activation has been found to be higher in CKD patients and animal models and is associated with an increased risk of cardiovascular disease." (PMID 37362429, 2023). "Meanwhile AhR has also been shown to mediate inflammation and cardiovascular disease in CKD patients." (PMID 37113297, 2023). "The pathogenesis driven by AhR varies among cardiovascular diseases, but includes inflammatory responses, immune responses, oxidative stress, and endothelial dysfunction." (PMID 35743162, 2022). "AhR is closely connected with cardiovascular diseases in terms of cardiac function, vascular development, and blood pressure regulation." (PMID 35743162, 2022). "In contrast, the activation of AHR by indolic uremic toxins is largely demonstrated to be harmful for endothelial cells and related to cardiovascular diseases, through the induction of pro-atherogenic and prothrombotic mechanisms." (PMID 32244284, 2020).
cardiovascular disease (continued). "AhR is thought to play an essential role in the vascular dysfunctions seen in patients with cardiovascular disease." (PMID 33415104, 2020). "The role of the AhR in the development of novel therapeutic agents for the treatment of cardiovascular diseases is also presented." (PMID 31638212, 2019). "Because many environmental pollutants contain exogenous aryl hydrocarbon receptor (AhR) ligands, increasing attention is being given to the relationship between AhR and cardiovascular diseases." (PMID 29984241, 2018). "Problems with AhR ligands and AhR transcripts can lead to abnormal activation of AhR, and result in an unbalanced cardiovascular system and cardiovascular diseases." (PMID 29984241, 2018). "Despite progress in our understanding of AhR-relating cardiovascular diseases, crosstalk between the cardiovascular system and the microenvironment is unclear." (PMID 29984241, 2018). "More recently, the functions of AhR in environmental adaption have been examined in the context of the occurrence, development, and therapy of cardiovascular diseases." (PMID 29984241, 2018). "With an increased understanding of the link between environmental pollutants and cardiovascular diseases, the impact of AhR on the cardiovascular system has become evident." (PMID 29984241, 2018). "We also discuss the potential contribution of AhR as a new potential factor in the targeted treatment of cardiovascular diseases." (PMID 29984241, 2018). "Modulating the effects of IS using therapeutic strategies targeting oxidative stress and AhR activation could limit the occurrence of cardiovascular disorders in CKD patients." (PMID 32260489, 2020). "Impairment of the antithrombotic properties of shear stressed endothelium by toxic AHR agonists could favor cardiovascular diseases in CKD." (PMID 32244284, 2020). "AhR is a potential drug or gene target for the treatment of cardiovascular diseases." (PMID 29984241, 2018). "In this review, we discuss the progress of AhR biology and toxicology, its pathophysiology roles in the heart and vascular systems, and the prospects as a therapeutic target for cardiovascular diseases, with the aim of providing a potential direction for the prevention and treatment of the diseases." (PMID 29984241, 2018). "The ability of tryptophan derived of uremic toxins to activate AhR may explain how these toxins contribute to cardiovascular diseases in CKD patients." (PMID 24599232, 2014). "Airborne particulate matter may activate oxidative stress and inflammatory responses via upregulation of the aryl hydrocarbon receptor (AhR), which in turn activates AhR-dependent pathways and induces respiratory diseases, cardiovascular diseases, and atherosclerosis." (PMID 34417533, 2021). "The AhR may be a potential target for the clinical treatment of cardiovascular disease." (PMID 31638212, 2019). "Given kynurenine’s potential to incite AHR-mediated inflammation, inhibitors of IDO present themselves as promising targets for the treatment of cardiovascular disease." (PMID 38731818, 2024). "The accumulation of uremic toxins has effects similar to those of AhR antagonists, making patients with CKD more prone to cardiovascular disease through a series of possible mechanisms." (PMID 33415104, 2020). "The role of AhR-activating uremic toxins in cardiovascular disease, and notably the role of IS, has been described." (PMID 24599232, 2014).